INS (insulin)
Diseases named in the same sentence as INS in open-access papers (continued):
Sharing a sentence is not in itself a finding about the gene and the disease.
diabetes (continued). "Cumulative childhood, adulthood, and lifelong insulin are associated with decreased retinal arteriolar diameter in adulthood in a population of participants without diabetes, independently of conventional cardiovascular risk factors." (PMID 39661465, 2024). "These comorbidities, insulin use, and/or pregnancy can make attaining or working towards physical activity recommendations more challenging for people living with diabetes and add complexity to the design and delivery of physical activity interventions by primary care providers ​." (PMID 39407129, 2024). "However, for PLWD in Zimbabwe, there can be a disrupted supply chain of essential medications, such as insulin, which can impede adherence, and can be exacerbated for people who have lived with diabetes for longer." (PMID 38439010, 2024). "With ongoing research and development, these pumps are likely to become increasingly sophisticated, addressing not only the physiological aspects of insulin delivery, but also the practical concerns of patients, ultimately improving diabetes management and quality of life." (PMID 39065641, 2024). "Oral repaglinide is a rapid-acting insulinotropic agent that reduces postprandial glucose by targeting early insulin release, and lowering postprandial glucose is considered to be an important factor in the reduction in long-term cardiovascular complications of diabetes." (PMID 39598478, 2024). "Treatments for diabetes that focus on improving insulin sensitivity might therefore have the potential to postpone or even prevent cognitive decline in patients with T2D." (PMID 38843768, 2024). "Diabetes is a major health concern that the next-generation of on-demand insulin releasing implants may overcome via personalized therapy." (PMID 39274135, 2024). "In this multicenter, open-label, and single-armed prospective study, 48 patients with diabetes (including type 1 and type 2) at 3 hospitals in Japan treated with insulin or glucagon-like peptide 1 receptor agonists and performing SMBG used the app-cloud cooperation system for 24 weeks." (PMID 38241065, 2024). "It is characterized by inadequate glycemic control, caused by either reduced insulin secretion (type 1 diabetes mellitus, T1DM) or by a reduced cellular response to insulin (type 2 diabetes mellitus, T2DM), which is the main type of diabetes, with a prevalence of the 90–95% of the total incidence." (PMID 39125904, 2024). "Type 1 diabetes mellitus (T1DM) is manifested as a decrease in endogenous insulin secretion." (PMID 38586619, 2024). "Since the levels of catalase were not changed in the diabetic heart with or without treatment, it is likely that the modification of oxidative stress biomarkers by diabetes, as well as due to insulin or sarpogrelate treatment, is site-specific in the oxidative stress pathway." (PMID 39057635, 2024). "Another mechanism could be attributed to poor diabetes regulation and higher levels of glycosylated hemoglobin in patients initiating insulin treatment." (PMID 39310536, 2024). "Indeed, glucose-lowering agents or insulin use because of misdiagnosis of the type of diabetes has led to hypoglycemia and other adverse effects in more than a third of these patients." (PMID 39408828, 2024). "Many clinical and preclinical studies have proven the beneficial effects of berberine in diabetes mellitus, mainly due to its ability to enhance insulin expression and potential antioxidant effects, as well as improving spatial reminiscence impairment in diabetic rats." (PMID 39758348, 2024). "In our study, nearly all patients were on pharmacological treatment of diabetes and the original beta cell function and insulin resistance may be altered." (PMID 37751894, 2024).
diabetes (continued). "The urgency to control and manage diabetes, and the critical roles those multiple aspects of diet (diet quality, macronutrient composition, eating frequency, etc.)play in diabetes management as well as in insulin use, justify a need to examine these aspects of insulin takers’ diets." (PMID 39458437, 2024). "Pde3b is involved in insulin signalization and is related to obesity and diabetes." (PMID 39484291, 2024). "Polyphenols, found in fruits such as apples and grapes, can manage diabetes by activating the AMPK pathway to improve insulin sensitivity, inhibiting α-amylase and α-glucosidase to slow carbohydrate digestion, as well as by enhancing the PI3K/Akt pathway for enhanced glucose uptake." (PMID 39519546, 2024). "Further exploration of the downregulated DEGs through GO and KEGG pathways enrichment analyses revealed strong associations with pancreatic islet genes that are critical in processes such as diabetes mellitus, insulin secretion and processing, and glucose homeostasis." (PMID 38916841, 2024). "However, in STZ-model of diabetes, pancreatic beta-cells are destroyed and insulin production vanishes." (PMID 39685849, 2024). "One study focused on histories of patients with diabetes and diabetes care plans (eg, insulin regimen, diet, and exercise plans) and patients’ self-monitoring of vital signs, and 1 study used self-monitoring data on daily activities, side effects, and patient-reported outcomes." (PMID 38686541, 2024). "Diabetes mellitus (DM), commonly known as diabetes, is a chronic metabolic disease that leads to persistently high blood glucose levels due to inadequate insulin secretion or insulin action." (PMID 39564359, 2024). "In the standard treatment for advanced diabetes, INS is supplied to compensate." (PMID 38313028, 2024). "An ANCOVA model controlling for covariates (sex, age, diabetes duration, insulin dose, BMI, time using insulin pump, and smoking behavior), showed that statistically significant differences (p = 0.001) in HbA1c levels persisted across all SES quartiles at the end of the follow-up period." (PMID 38273326, 2024). "Regarding the distribution of the participants according to history of diabetes, diabetes treatment characteristics, and medical history, the majority of the patients (67%) had diabetes for longer than 10 years, while 22% had used insulin for the same period." (PMID 39715819, 2024). "Our study showed that glycemic control in insulin users has remained stable or improved between 2012 and 2019 despite aging population and in parallel with introduction of new treatment options, providing valuable insight into Finnish national diabetes care." (PMID 38273701, 2024). "Treatment of postoperative hyperglycaemia with insulin may help improve results and also determine whether dexamethasone would be safe in people being treated with insulin for diabetes." (PMID 39028762, 2024). "reviewed the characteristics of the Chinese MDM population and found that 92.6% had a young age at diabetes diagnosis (≤ 45 years), 94% had a BMI <24 kg/m2, 85.4% had abnormal hearing, 61.4% received insulin injections, and 98% had a maternal history of hyperglycemia or diabetes." (PMID 39749018, 2024). "Among 372 Pima individuals without diabetes who participated in metabolic testing, the presence of the risk allele (G allele of +8130 G/A) was found to be correlated with diminished insulin action." (PMID 39273144, 2024). "For diabetes, pancreatic cells could be modified to produce insulin or insulin-regulating miRNAs, providing long-term control over glucose levels." (PMID 39684593, 2024). "The OLE of O. europaea Verdeal might also improve both insulin sensitivity and the secretory capacity of pancreatic β-cells, mimicking metformin effects in patients with type 2 diabetes mellitus (T2DM)." (PMID 38543060, 2024).
diabetes (continued). "In addition, other studies found am ethnic medicinal plant from the same genus, Acorus calamus L., has therapeutic effects on diabetes and cardiovascular complications through a mechanism of insulin sensitization." (PMID 38567357, 2024). "In terms of diabetes therapy, insulin injection was the most commonly used treatment modality among 222 (55.1%) participants, whereas 29% (n = 117) used oral hypoglycemic pills (sulfonylurea, thiazolidinediones, and others), and 15.9% (n = 64) followed a healthy diet and oral metformin." (PMID 38435926, 2024). "Terpenoids have shown anti diabetes properties in vivo and in vitro studies, which can increase insulin secretion in body tissues, promote the translocation of GLUT4 to increase glucose uptake, protect pancreatic cells and improve the expression of inflammatory factors." (PMID 39045049, 2024). "Participants were excluded if they used insulin or multiple medications for diabetes." (PMID 39246956, 2024). "Indeed, the discovery of a second hormone capable of boosting muscle glucose absorption in addition to insulin would have substantial implications in diabetes mellitus, where insulin insufficiency or resistance reduces glucose tolerance." (PMID 39796447, 2024). "In this descriptive nationwide non‐interventional register study, we assessed the clinical and demographic characteristics, medication purchases, BI treatment patterns, and glycemic control in people with insulin‐treated diabetes in Finland between 2012 and 2019." (PMID 38273701, 2024). "Since the oral glucose tolerance test (OGTT) is frequently used for the classification and diagnosis of diabetes and pre-diabetes, the additional blood samples taken to calculate a surrogate measure of insulin secretion are relatively inexpensive and time-efficient to collect." (PMID 39013634, 2024). "Insulin is utilized as a treatment for diabetes by millions of patients worldwide." (PMID 37611907, 2024). "Insulin resistance (IR) is a pathological state characterized by impaired insulin responsiveness, requiring elevated level of insulin to maintain glucose homeostasis in both peripheral tissues and the brain, a key feature of Type 2 diabetes mellitus (T2DM) and metabolic syndrome." (PMID 39882263, 2024). "Overall, 21.8% of participants had some progression of DR during the study time frame, which is expectedly lower than progression rates seen in these earlier studies when use of intensive insulin therapy was being introduced and before use of diabetes technologies." (PMID 38446483, 2024). "Clarifying the interaction between the psEV conferred upregulation of ANXA1 and increases in insulin synthesis warrants further investigation and may hold promise for the development of therapies to treat diabetes." (PMID 39432712, 2024). "The use of insulin is pivotal in the management of neurological disorders other than diabetes." (PMID 38441832, 2024). "Chronic exposure of the pancreas to MBEHQ‐induced oxidative stress may disrupt pancreatic function, impair insulin production, and contribute to the development of pancreatic disorders such as pancreatitis or diabetes." (PMID 39313936, 2024). "The clinical relevance of our observation was also demonstrated by the significant association between “Glucose‐insulin‐AMPK” expression with both BMI and presence of diabetes in the GTEx cohort, and also correlated significantly with BMI and total fat mass in the Umea cohort." (PMID 38561245, 2024). "Despite the insulin therapy and dietary interventions, our patient's glycemic control remained stable, but no significant improvement in weight was observed, emphasizing the difficulty of managing obesity-related diabetes in PWS." (PMID 39135667, 2024). "Ghrelin increases blood glucose levels by inhibiting insulin release from beta cells, participates in the growth and proliferation of beta cells, and prevents beta cell apoptosis, which has high research value for the treatment of diabetes." (PMID 39595573, 2024).
diabetes (continued). "Following the onset of diabetes, insulin needs are often low among preschool children." (PMID 38785359, 2024). "Among participants with diabetes, nearly 92% had access to healthcare facilities, suggesting that the majority may have received treatment, such as insulin therapy." (PMID 38791732, 2024). "However, when insulin is given later (10 weeks after diabetes induction), only a partial improvement was observed." (PMID 39139399, 2024). "The efficiency of the counter-regulatory system decreases with the duration of diabetes due to the passive absorption of insulin into the bloodstream from the site of its administration, reduced ability to secrete glucagon by pancreatic beta-cells, and impaired adrenaline secretion." (PMID 38673509, 2024). "Insulin quickly became the cornerstone of diabetes management." (PMID 39691108, 2024). "In addition, according to healthcare professionals, patients lack sufficient understanding of diabetes and knowledge in relation to insulin titration and dose adjustment, hampering the effective use of insulin." (PMID 38391858, 2024). "Diabetes is a long-term condition caused by insufficient insulin, which can be due to a lack of insulin production or insensitivity to insulin." (PMID 39000954, 2024). "In the pancreas, SFAs inhibit the synthesis and secretion of insulin by pancreatic β cells and promote β-cell apoptosis, leading to a decrease in the number and function of β cells, and thus contributing to the development of diabetes mellitus." (PMID 38501107, 2024). "The stimulatory effect of insulin on AVP secretion and the potency of insulin to reduce AVP-induced hyperglycemia are diminished in diabetes mellitus and insulin resistance, which may result from inappropriate generation of gasotransmitters and free radicals." (PMID 39769071, 2024). "MiR-126 has an antioxidative protective role on endothelial cells, and miR-484 in diabetes is known since it may be a regulator of insulin expression by decreasing it in the β pancreatic cells in response to increased glucose." (PMID 39519313, 2024). "Given these problems, many researchers made remarkable efforts to analyze diabetes complicating depression from different aspects, including insulin resistance, stress and Hypothalamic–Pituitary–Adrenal axis, neurological system, oxidative stress, and inflammation." (PMID 37927197, 2024). "Diabetes mellitus Type 2 is a common metabolic illness, and it occurs when the pancreatic cells are unable to produce sufficient insulin for maintaining a normal level of glucose in the blood, or when the pancreatic cells become resistant to insulin." (PMID 39130669, 2024). "Yet, the most pronounced change in islet autoimmunity that we noted was against neoantigen INS-DRiP, which may imply that this could be a driving force in progression to diabetes." (PMID 38596681, 2024). "Insulin-induced hypoglycemia and fear of hypoglycemia (FoH) are major limiting factors in glycemic management and a significant concern for children and adolescents with diabetes and their caregivers." (PMID 38894740, 2024). "Additionally, PNX’s impact on insulin sensitivity and glucose metabolism positions it as a candidate for addressing obesity-related metabolic disorders, such as diabetes, by improving glucose utilization and enhancing insulin sensitivity." (PMID 39057043, 2024). "He developed diabetes in 2019 and started insulin therapy by multiple daily injection scheme." (PMID 38779453, 2024). "Besides glucose, other markers of diabetes, including glycated hemoglobin, insulin, and cellular responses, have been detected using microfluidic devices." (PMID 38509342, 2024). "In addition, they were taller with a lower BMI but higher ABSI, were older at diabetes diagnosis but had a longer duration of diabetes, and were more likely insulin treated." (PMID 37930807, 2024). "Inhibition of JNK alleviates diabetes symptoms and improves insulin sensitivity in T2DM rats." (PMID 39272602, 2024).
diabetes (continued). "We therefore hypothesise that changes in methylation at this locus may contribute to a loss of beta cell hierarchy and connectivity, potentially contributing to defective insulin secretion in some forms of diabetes." (PMID 38512414, 2024). "In this three-year retrospective study, data from 51 patients with type 1 or type 2 diabetes mellitus (DM), receiving a minimum of 3-4 insulin injections per day and self-monitoring their blood glucose (SMBG) four times a day, were derived from our internal medicine residency primary care clinic." (PMID 39149659, 2024). "However, attenuated hormonal response and hypoglycaemia unawareness are still a problem even with advancements in insulin delivery methods and novel diabetes technologies." (PMID 38392992, 2024). "Excessive activation of the sympathetic nervous system could potentially play a role in metabolic issues, including insulin resistance leading to increased insulin levels, disrupted glucose metabolism, diabetes, and abnormal lipid levels." (PMID 39081789, 2024). "Although patients who had had T2DM for longer had a slightly better lipid profile (with higher HDL and lower triglyceride levels) than those with a shorter duration of diabetes, they were more often regular insulin users, hypertensive (with a higher systolic blood pressure), and had a lower eGFR." (PMID 39408563, 2024). "More strikingly, stem cell-derived pancreatic pseudoislets generated in vitro could potentially become an infinite source of insulin-secreting β-cells for a potential diabetes therapy." (PMID 38966213, 2024). "The preservation of intact HA in non-T1DM pre-existing diabetes may be explained by the presence of functional insulin-counter-regulatory hormones and the short duration of diabetes, as the majority of these individuals had diabetes for less than five years." (PMID 40071056, 2024). "Despite poor glycaemic control, there is a practice of increasing the dose of oral anti-diabetics or adding more drugs to the regimen due to the common perception that low endogenous insulin secretion is related to type 1 diabetes mellitus only and patient’s poor compliance with injectables." (PMID 38654804, 2024). "This study identified significant positive associations between ED and factors such as diabetes duration, microvascular complications, insulin therapy (with or without oral agents), comorbid conditions, and the use of non-diabetes medications." (PMID 40438430, 2024). "Additionally, the frequent encounters with primary care providers were also found to significantly increase non - insulin diabetes medication adherence among newly diagnosed T2DM patients with poor adherence at baseline (OR: 1.12, 95 % CI (1.10, 1.15))." (PMID 38279105, 2024). "However, treatments with T2DM + SITG10 and T2DM + SITG30 for 30 days significantly improved insulin levels to 3.192 ± 0.151 (p < 0.001) and 3.423 ± 0.161 (p < 0.001), respectively, compared to the diabetes-induced group." (PMID 39766390, 2024). "Of the 585 individuals from the Hoorn Diabetes Care System (DCS) cohort, 69 required insulin during follow-up (1.0–11.4 years); of the 571 individuals in the Genetics of Diabetes Audit and Research in Tayside Scotland (GoDARTS) cohort, 175 required insulin during follow-up (0.3–11.8 years)." (PMID 38374450, 2024). "However, the great discovery that revolutionized this field came from the Canadian doctor Frederick Banting, who together with his student and assistant Charles Best, managed to isolate insulin and treat a patient with diabetes on 23 January 1922." (PMID 38540146, 2024). "The findings of our study align with recent studies demonstrating an increased K score (using the same K measuring tool) in patients with T2DM, including insulin users, after the application of targeted education programs like diabetes self-management education (DSME) compared to control cases." (PMID 39273732, 2024).